PDPN (podoplanin)
Diseases named in the same sentence as PDPN in open-access papers (continued):
Sharing a sentence is not in itself a finding about the gene and the disease.
tumor (continued). "Our research also shows that podoplanin+ ptLVD is associated with lymphatic metastasis, Pathologic stage and Ki67%, and not with histologic type or Tumor differentiation." (PMID 19216806, 2009). "Confocal imaging revealed that 3% of Podoplanin+ tumor lymphatic endothelial cells (TLEC) as well as 3.5% of Prox-1+ or LYVE-1+ TLEC co-expressed GFP, indicating that approximately 3% of tumor-surrounding lymphatic endothelial cells are derived from the bone marrow." (PMID 19759906, 2009). "It has been suggested that the interaction of CLEC-2 with podoplanin, which involves O-glycans, may be involved in promoting tumor growth and/or metastasis, and could therefore be a target for therapeutic intervention." (PMID 19025564, 2009). "Also here, GFP+ cells were found integrated into tumor-associated lymphatic endothelium, detected by LYVE-1 or Podoplanin expression." (PMID 19759906, 2009). "Finally, D2-40 staining of tumor cells was also evaluated, in order to study the potential role of podoplanin in neoplasia development and invasion." (PMID 18072963, 2007). "Accordingly, we can hypothesize that tumor cells of same histological pattern could also differently express podoplanin according to the organ where the neoplasia grows." (PMID 18072963, 2007). "Here, we revisit the mechanism of podoplanin-mediated tumour invasion." (PMID 17179989, 2007). "Conceivably, the elimination of PDPN+ cells in the MB TME may reduce the immunosuppression exerted by different types of mesenchymal stromal cells allowing the triggering of NK or T cell responses as shown in other tumor models." (PMID 40677711, 2025). "Elevated podoplanin expression within the tumor microenvironment may result in the local sequestration of CLEC-2, either via stable ligand-receptor binding or receptor internalization at the tumor-platelet interface, ultimately decreasing the levels of free, circulating CLEC-2 detectable in plasma." (PMID 41209555, 2025). "Interestingly, most tumor cells in AS co-expressed PDPN and markers of blood vessel phenotypes (e.g., CD31, ERG, vWF), an unusual combination in normal vessels, suggesting their potential derivation from a common precursor of lymphatic and blood vascular endothelium." (PMID 40666093, 2025). "Interestingly, the role of Podoplanin-expressing CAFs varies across different tumor types." (PMID 40094065, 2025). "For this reason, the PDPN+ vessel density may be a better indicator of the lymphatic remodeling within the tumor microenvironment, and an additional fibroblast-specific marker, such as α-smooth muscle actin, could be used to distinguish between the populations." (PMID 39998766, 2025). "Furthermore, future studies could explore the relationship between distinct patterns of tumor infiltration (e.g., pushing vs. spray-like invasion) and podoplanin expression." (PMID 40542163, 2025). "Disentangling the relative contributions of tumor cell-derived versus stromal cell-derived PDPN represents a vital direction for future research, as it would refine therapeutic strategies aimed at the PDPN pathway to more precisely overcome microenvironment-driven mechanisms." (PMID 41573582, 2025). "In addition, PDPN regulates cell proliferation, migration, invasion, epithelial-mesenchymal transition (EMT), and stemness associated pathways, all of which are critical for the tumor development." (PMID 38167452, 2024). "We speculate that there may be interactions between PDPN and tumor-infiltrating immune cells." (PMID 38167452, 2024). "Also, areas of tumor that contain more mature and less active cells lack podoplanin staining." (PMID 38962078, 2024). "However, how podoplanin contributes to tumour metastasis is still unclear." (PMID 38561690, 2024). "Interestingly, several studies demonstrated that cancer cells and PDPN‐expressing CAFs might contribute to a malignant microenvironment for tumour tissues." (PMID 36156321, 2023).
tumor (continued). "Moreover, a higher number of total T cells accumulated in tumor nests accompanied by significantly decreased expression of PanCK+ tumor cells and depletion of PDPN+ CAFs in the tumors treated with FAP-CAR T cells followed by FAP-CAR and Meso-CAR T cells than in other combinations." (PMID 37607999, 2023). "Interestingly, PDPN deletion in macrophages reduced tumor lymphangiogenesis and lymph invasion." (PMID 37898403, 2023). "Therefore, verification of the relationship between podoplanin expression which reflects tumor aggressiveness, and ENE subcategories could be contributed to establish the clinical implication of ENE progression." (PMID 35256682, 2022). "Circulating tumor cells may be a source of circulating PDPN." (PMID 35814405, 2022). "Consequently, the mechanisms via which podoplanin mediates tumor progression in EMPD could soon be clarified in vivo." (PMID 35163233, 2022). "The mucin-type transmembrane glycoprotein PDPN is important for the development of multiple organs, and expression of PDPN in a large number of human tumors suggests that the protein may have a functional role in tumor development or progression." (PMID 36059614, 2022). "Furthermore, PDPN modulates signal transductions that regulate cell proliferation, differentiation, migration, invasion, epithelial-to-mesenchymal transition, and stemness, all of which are crucial for the malignant progression of tumor." (PMID 35159384, 2022). "Besides, tumor-associated glycoforms of conventional antigens, including SLAMF7, CLEC14A, PDPN, PODXL, and CD44, could also be ideal target antigens." (PMID 36261831, 2022). "To understand if PDPN may be playing a role in tumor aggressiveness and radioresistance in additional cell lines and contexts, we performed a series of experiments using adherent cell lines, which are grown in serum (unlike GSCs, which are grown in serum-free conditions)." (PMID 36059614, 2022). "Similarly, the expression of podoplanin on fibroblasts may be responsible for M2 polarization and immunosuppression of the tumor microenvironment." (PMID 36230508, 2022). "Therefore, CLEC-2 may play an important role in tumor-induced thromboinflammation, and chronic long-term exposure to inflammatory cytokines induces podoplanin expression." (PMID 34177942, 2021). "In light of our results, it is tempting to speculate that modulation the PDPN/CLEC-2/CD177 axis may represent an alternative approach to remove obstacles for T cell entry into tumor beds, by lessening CAF contractility and ultimately decreasing tissue stiffness." (PMID 34879110, 2021). "Moreover, PDPN overexpression is also involved in TCIPA-induced tumor promotion and progression." (PMID 34987523, 2021). "C-type lectin domain family 1 member B (CLEC1B), a tumor platelet-related molecule secreted by activated platelets in the peri-tumor area, could affect thrombus formation and hematogenous metastasis of tumors through interactions with podoplanin." (PMID 34627241, 2021). "In particular, T helper (Th) 1 and Th17 cells play a role in the irAEs of tumor immunotherapy, especially the protein podoplanin on Th17 cells, the depletion of which may induce auto-immune disease by enhancing the infiltration of T cells, as well as inhibit tumor growth." (PMID 35111155, 2021). "In addition, platelet CLEC-2, whose ligand podoplanin is expressed on the surface of tumor cells, may facilitate tumor metastasis." (PMID 34360659, 2021). "Thus, further research into the role of PDPN in tumor biology is necessary." (PMID 32380790, 2020). "However, there are few reports on the expression of dog PDPN (dPDPN) in canine tumors, and the association between dPDPN and tumor malignancy has not been elucidated." (PMID 32380790, 2020).
tumor (continued). "Furthermore, a cancer-specific mouse–dog chimeric anti-PDPN antibody (P38Bf) originating from mouse monoclonal PMab-38 were shown to reduce immunological reactions, and P38Bf demonstrated strong anti-tumor effects in a PDPN-overexpressed CHO-K1 cell xenograft mouse model." (PMID 33238582, 2020). "Therefore, it is considered that PDPN enhances tumor malignancy and thus could be used as a therapeutic target for some types of tumors." (PMID 32380790, 2020). "Many reports have demonstrated that PDPN expressed on human and canine tumors is associated with tumor malignancy through the promotion of malignant proliferation and epithelial–mesenchymal transition (EMT), and that it promotes metastasis by enhancing tumor cell migration and platelet aggregation." (PMID 33238582, 2020). "Since GBM-infiltrating macrophages, microglia, and myeloid-derived suppressor cells have been shown to hinder T-cell proliferation, infiltration and activation we addressed the question whether PDPN+ myeloid cells promote tumor development by intervention with the T-cell compartment." (PMID 30972297, 2019). "Therefore, platelet activation by CLEC-2/podoplanin interaction facilitates tumor metastasis." (PMID 31011556, 2019). "Thus, the targeted ablation of podoplanin positive myeloid cells could be included in combinatorial cancer therapies to enhance immune-mediated tumor elimination." (PMID 30972297, 2019). "Additional experiments would be required to validate this cascade in vivo and furthermore, to show that in the absence of PDPN+ myeloid cells, T-cells not only infiltrate the tumors but also execute cytotoxic reactivity against the tumor cells causing the observed prolonged survival." (PMID 30972297, 2019). "Additionally, SZ168 recognized PDPN in immunohistochemical analyses of tumor tissue sections." (PMID 31208371, 2019). "The immunohistochemical factors of lymphatic endothelial cells, such as D2-40 (podoplanin), lymphatic vessel endothelial hyaluronic acid receptor 1 (LYVE1), and VEGF receptor-3 (VEGFR-3), indicate the lymphatic vessel count associated with the tumor which can metastasize to lymph nodes." (PMID 31870093, 2019). "Podoplanin is a pro-invasive glycoprotein with in large unknown function which is expressed on lymphatic endothelia and other specialized tissues but also up-regulated on tumor cells and on fibroblasts in reactive tissues such as synovitis in RA." (PMID 31275320, 2019). "However, the association of tumour-associated podoplanin and VTE in cancer patients has not been established apart from in patients with brain cancer." (PMID 30314362, 2018). "Because these growth factors are contained in granules of platelets, they are released during PMPA, may promote tumour growth, and induce expression of podoplanin, which could activate platelets; therefore, intratumoral PMPA can initiate tumour malignant progression cycle." (PMID 28642617, 2017). "However, the tumour volume of A549/PDPN was increased in vivo." (PMID 28642617, 2017). "Hence, podoplanin expression on tumour cells could serve as a predictive biomarker for individualised therapy." (PMID 28737696, 2017). "Thus, the release of these growth factors may further accelerate podoplanin-mediated platelet aggregation and promote tumor growth and metastasis." (PMID 28674748, 2017). "Therefore, one may conclude that PDPN plays a dual role in tumor progression and tumor metastasis, via the activation of the ROCK pathway in cancer cells and via platelet aggregation." (PMID 28059107, 2017). "Moreover, we identified two MPM effusion-related factors with clinical value: CD4+ T cells were significantly correlated with better response to chemotherapy, while the percentage of PD-L1+ podoplanin (PDPN)+ tumor cells is a significant prognostic factor for worse outcome." (PMID 29163783, 2017).
tumor (continued). "Increased podoplanin expression following treatment with TGF-β or supernatants of tumour-platelet reactants might lead to further acceleration of tumour malignancy through enhanced tumour-platelet interaction." (PMID 28176852, 2017). "However, the verification using endogenously podoplanin-expressing tumor cells is still restricted." (PMID 28674748, 2017). "Also, the chemokine receptor −4 (CXCR4) reactivity was also noticed in tumor cells with membranous, cytoplasmic and even nuclear pattern Moreover, the podoplanin tumor cell reactivity, with a membranous pattern, was more obvious at the advancing edge, at the periphery of tumor proliferations." (PMID 27871286, 2016). "Thus, PDPN may present an opportunity to interrupt oncogenic signaling cascades that induce its expression such as those initiated by a number of tumor promoters including Ras, FGF/BMP, Src, EGF, and TGFβ." (PMID 25826087, 2015). "Next, we examined whether CAFs-PDPN influences tumor engraftment or tumor volume." (PMID 25909164, 2015). "However, the exact mechanism of PDPN action in tumor cells is still unclear; in some cases, PDPN expression mediates the downregulation of E-cadherin and promotes EMT (Martín-Villar, 2006), while in others, PDPN expression enhances tumorigenesis and metastasis in the absence of EMT." (PMID 22988448, 2012). "Thus, it was postulated that PDPN expressing stroma could act as a physical barrier to tumor cell invasion into surrounding tissues." (PMID 22988448, 2012). "Our results showing that podoplanin expression levels decreased with primary tumour size evidence a higher proportion of podoplanin-positive cells in small tumours and podoplanin-positive staining in those tumours could reflect a higher proportion of TICs, rather than a higher invasive potential." (PMID 20196862, 2010). "Histologically, podoplanin-positive cells were specifically located in most cases at the basal region of squamous cell carcinoma tumour nests, close to the surrounding stromal cells and the tumour-microenvironment interaction plays a decisive role in cancer progression." (PMID 20196862, 2010). "Furthermore, those cases showing diffuse podoplanin staining had a poorer disease specific-survival than the cases that displayed a focal expression pattern in the periphery of tumour nests, but there was only a borderline statistical difference (Log-rank test, P = 0.08)." (PMID 20196862, 2010). "Hence the role of podoplanin in tumour initiation and progression remains elusive." (PMID 20196862, 2010). "In contrast, Podoplanin or Prox-1 were not expressed by these tumor-associated macrophages (TAM)." (PMID 19759906, 2009). "Immunostaining for lymphatic markers such as LYVE-1 and podoplanin in routine histological work-up of tumour samples might be warranted if future studies reveal a correlation between tumour-induced lymphangiogenesis and prognosis of the tumour in terms of metastasis and recurrence rate." (PMID 19628489, 2009). "However, some important questions concerning the function of podoplanin in tumours remain open." (PMID 17179989, 2007). "As CD31 and podoplanin RNA were both greatly reduced in the MDAMB231 tumours, this may account for the fact that there was decrease in growth of the MDAMB231 tumours following Celecoxib, even though the increase in apoptosis failed to reach statistical significance." (PMID 17285134, 2007). "Upon PDAC progression (endpoint), DKK3+PDPN+ CAFs increased in both KC and DKC tumors, predominating in DKC but remaining comparable to DKK3+CK19+ tumor cells in KC, indicating a shift of DKK3 expression from epithelial to stromal compartments." (PMID 41147409, 2026). "Inhibitory targeting of PDPN with CY12-RP2 represents a promising therapeutic approach capable of disrupting this immunosuppressive pathway and reversing tumor immune escape." (PMID 41573582, 2025).
tumor (continued). "PDPN+ area coverage peaked at 1 day post-SA-HFIRE, while PDPN vessel density peaked at 3 days post-treatment within the viable tumor region." (PMID 39998766, 2025). "In conclusion, our study refines concepts of p‐EMT and tumor cell invasion in HNSCC and identifies PDPN and HIC1 as potential therapeutic targets for future development." (PMID 40736379, 2025). "To confirm that the vast majority of CAFs are indeed tdTomato+, we performed immunofluorescence staining of the fibroblast markers podoplanin (PDPN) and α‐smooth muscle actin (αSMA) on tissue sections of a primary tumor engrafted in a mT/mG mouse." (PMID 39924882, 2025). "Tumor cells in angiomatoid ATC display epithelial markers (cytokeratins, EMA), and occasionally stain with endothelial markers as well as PAX8, TTF1, and podoplanin." (PMID 40214777, 2025). "To clinically evaluate the expression levels of PDPN, CD31, and CCL2 in GC samples, we assessed protein levels in 400 tumor and 73 normal gastric tissue samples." (PMID 39764562, 2025). "To analyze the tumor invasive feature, we performed the double staining of CK7 together with podoplanin, a lymphatic vessel marker." (PMID 41028519, 2025). "To further investigate the proangiogenic and tumor‐promoting effects of PDPN(+) CAFs in vivo, we inoculated MKN45 cells subcutaneously into mice, either alone or in combination with PDPN(+) CAFs or PDPN(−) CAFs." (PMID 39764562, 2025). "Furthermore, to verify the specific effects of exo-miR-224-3p on lymphangiogenesis in GC, podoplanin antibody, which is a specific marker of HLECs that can reveal the status of lymphangiogenesis in and around tumors by IHC, was used to perform IHC on the removed tumor tissues." (PMID 39866224, 2025). "Lastly, podoplanin (PDPN, D2-40) is frequently overexpressed in invasive SCC, including SCCNU, and highlights tumor-stroma interfaces and lymphatic channels." (PMID 41008750, 2025). "Mechanistically, F. rodentium produced acetate, which suppressed the expression of PDPN on CD8+ T cells and that of C-type lectin-like receptor 2 (CLEC-2) on tumor cells." (PMID 40693815, 2025). "PDPN on lymph node stromal cells has been shown to suppress T cell proliferation and enhance tumor growth by restricting antitumor CD4+ T cell function, whereas depletion of stromal PDPN bolsters antitumor T cell activity and limits tumor progression." (PMID 41573582, 2025). "Collectively, our data suggest that the AKT/IKK/NF‐κB pathway in PDPN(+) CAFs regulates CCL2 secretion, which subsequently stimulates angiogenesis and tumor growth." (PMID 39764562, 2025). "These cells express podoplanin (D2-40) and activate the Wnt/beta-catenin pathway, increasing MMP secretion and facilitating vessel wall degradation and tumor cell intravasation." (PMID 40647432, 2025). "Taken together, our study demonstrated that F. rodentium produced acetate, which suppressed the expression of PDPN on CD8+ T cells, and that of CLEC2 on tumor cells." (PMID 40693815, 2025). "Within the 5-year survivor cohort, there was significant (P < 0.05) enrichment of cellular interaction between PDPN+ CD21+ B cells, CD21+ B cells, Proliferating cells, as well as Lymphatic Endothelial cells with Tumor cells." (PMID 39333065, 2024). "Moreover, the study proposed that GBM cells expressing PDPN generate a unique type of systemic prothrombotic disturbances in vivo due to extracellular vesicles containing PDPN, underscoring the potential synergy between various coagulants in promoting microthrombosis within the tumor mass." (PMID 39682237, 2024). "We assume that, in our setting, the tumor cells attract and activate platelets through either tumor cell podoplanin-platelet CLEC-2 or tumor cell integrin-vWF-platelet GPIb interactions." (PMID 38764040, 2024). "The three subsets identified as more prevalent in the tumour (CAF-S1, CAF-S4 and CAF-S5) were investigated by staining for CAF markers FAP, αSMA, PDPN, CD90 and FSP1 in a cohort of 163 patients that were part of a TMA." (PMID 38582812, 2024).